USP53 (ubiquitin specific peptidase 53)
Diseases named in the same sentence as USP53 in open-access papers (continued):
Sharing a sentence is not in itself a finding about the gene and the disease.
cancer (10 papers, 2019 to 2025). A tumor composed of atypical neoplastic, often pleomorphic cells that invade other tissues. "Incorporating RCC1 into biomarker panels, alongside SGOL2 and USP53, could improve diagnostic accuracy and enable more effective, targeted cancer treatments." (PMID 40163507, 2025). "Furthermore, the overexpression of USP53 has been reported to induce cell death in various cancers, which indicates that USP53 is closely related to cell death regulation." (PMID 40822127, 2025). "RCC1, along with genes like SGOL2 and USP53, could form a prognostic biomarker panel to assess cancer aggressiveness and predict patient outcomes." (PMID 40163507, 2025). "Our data indicate that USP53 inhibits cancer cell proliferation and migration." (PMID 33973730, 2021). "The intersection of statistically significant cancer species in the four analyses contained BRCA, THCA, UCEC, LUSC, LUAD and KIRC, all of which showed down-regulated expression of USP53 compared with normal tissues." (PMID 39044157, 2024). "Next, we examined the protein expression level of USP53 in breast normal (MCF10A cell line) and cancer cell lines (T47D, MCF-7, MDA-MB-468, and MDA-MB-231 cell lines)." (PMID 37894400, 2023). "Although the role of USPs in cancer has been increasingly recognized by scholars, the function and specific mechanism of USP53 in malignant tumors have been lacking corresponding research, which needs to be further explored." (PMID 39300775, 2024). "To mention only a few, we have observed different expression of the CTCFL gene—oncogene—which is tested as a target gene in the immunotherapy of cancer, PADI2—a novel angiogenesis-regulating gene, or USP53—which is a novel molecular biomarker for weight control." (PMID 31756991, 2019). "However, there are no reports on the specific molecular mechanism of USP53 in cancer." (PMID 33973730, 2021).
infection (2 papers, 2021). The state of being infected such as from the introduction of a foreign agent such as serum, vaccine, antigenic substance or organism. "To test the effect of USP53 on proliferation in ccRCC, we inserted the USP53 gene into a plasmid vector, packaged it into a lentivirus, and constructed a cell line stably expressing USP53 by infection with Caki‐1 and 786‐O." (PMID 33973730, 2021).
mental illness (1 paper, 2023). "Since no data evidenced prior expression of USP53 in the CNS or involvement in any psychiatric disorder, functional studies were performed." (PMID 37895270, 2023). "Since the literature on USP53 lacked relevance to mental illness or CNS expression, studies were conducted which revealed USP53 localization in regions of the hippocampus (CA 1–3) and granular dentate." (PMID 37895270, 2023). "USP53 had limited functional data without published relevance to mental illness." (PMID 37895270, 2023).
USP53 also shares sentences with these, for which no sentence is quoted: intrahepatic cholestasis (2 papers); atherosclerosis (1); bone disorder (1); Hepatic hemangioma (1); hypertrophic cardiomyopathy (1); influenza (1); Intellectual disability (1); liver cancer (1); liver hemangioma (1); neoplastic disorders (1); renal cell carcinoma (1); respiratory failure (1); Tetralogy of Fallot (1).